NPIPB8 (nuclear pore complex interacting protein family member B8)
Tractability: No criterion of Open Targets' tractability assessment is met for any kind of drug.
Gene: Protein-coding gene on chromosome 16 (28,637,654 to 28,658,744, forward strand). Ensembl gene ENSG00000255524.
Subcellular location (Human Protein Atlas): Nucleoplasm
Genetic constraint (gnomAD): Loss-of-function variants: 3 observed, 3.03 expected, observed/expected ratio (o/e) 0.99, 90% interval 0.43 to 1.85. That is too few expected variants to judge how well the gene tolerates losing a copy. Missense variants: 47 observed, 30.07 expected, observed/expected ratio (o/e) 1.56, 90% interval 1.23 to 1.9. Synonymous variants: 18 observed, 12.53 expected, observed/expected ratio (o/e) 1.44, 90% interval 0.98 to 1.9.
Homologues: Paralogues in human: NPIPB9 (99% identical), NPIPB6 (94% identical), NPIPB7 (91% identical), NPIPB15 (88% identical), NPIPB13 (77% identical), NPIPB5 (77% identical), NPIPB12 (76% identical), NPIPB11 (76% identical), NPIPB4 (76% identical), NPIPB2 (62% identical), NPIPA3 (60% identical), NPIPA2 (60% identical), and 7 more.